CCL20 (C-C motif chemokine ligand 20)
Diseases named in the same sentence as CCL20 in open-access papers (continued):
Sharing a sentence is not in itself a finding about the gene and the disease.
colorectal tumor (3 papers, 2014 to 2024). "Expression of CCR6, the receptor for CCL20 in human colorectal tumors and adjacent uninvolved colon was measured by semi quantitative RT-PCR." (PMID 24866282, 2014).
cutaneous T-cell lymphoma (3 papers, 2016 to 2018). "Also, recent study suggests an IL-22/STAT3/CCL20 signal cascade in cutaneous T-cell lymphoma." (PMID 26901187, 2016). "We recently demonstrated that upregulation of a chemokine receptor CCR6 and its ligand CCL20 led to metastasis of advanced cutaneous T-cell lymphoma (CTCL) cells, suggesting the involvement of CCL20-CCR6 interaction in initiating CTCL cell metastasis." (PMID 26789110, 2016).
cystic fibrosis (3 papers, 2020 to 2024). Autosomal recessive disorder caused by pathogenic variants in the CFTR gene (cystic fibrosis transmembrane conductance regulator), which encodes a chloride and bicarbonate channel expressed in epithelial cells, and follow the diagnosis criteria. "Taken together, the here acquired results suggest that pathologically increased CCL20 levels in cystic fibrosis airways induce CCR6-mediated lung homing of circulating human ILC2s." (PMID 32457736, 2020). "CCL20 is produced by airway epithelia and is increased during cystic fibrosis, as revealed by abundant CCL20 levels in BAL fluid from patients with cystic fibrosis." (PMID 39768150, 2024). "CCL20 levels were shown to be higher in cystic fibrosis patients’ BAL compared to healthy BAL, implying that CCL20 plays a function in the respiratory immune defense." (PMID 36648852, 2023).
Granuloma (3 papers, 2013 to 2022). A compact, organized collection of mature mononuclear phagocytes, which may be but is not necessarily accompanied by accessory features such as necrosis. "MMP3, CCL20 and CCL22 showed significance increase in tuberculoid as compared to the lepromatous lesions adding support to the increased lymphocytes seen in BT granulomas." (PMID 23936569, 2013).
Hepatitis (3 papers, 2024 to 2025). Inflammation of the liver. "CCL20 from iMac and T cells and CXCL8 from iMac were the top two upregulated genes in the hepatitis phase (Right)." (PMID 39135698, 2024). "We also conducted double labeling of CCL20 and CXCL8 with CD68 and CD3, respectively, on liver biopsy samples from HBeAg‐positive hepatitis patients." (PMID 39135698, 2024).
Hypertension (3 papers, 2017 to 2022). The presence of chronic increased pressure in the systemic arterial system. "Meanwhile, we found that C5AR1, CCL4L2, CCL4, CCL20, CD163, CXCL3, and CXCL12 were only expressed in disease a, suggesting the recruitment of inflammatory factors and promotion of the inflammatory response were both more obvious in hypertension-induced AD." (PMID 35800890, 2022).
influenza infection (3 papers, 2021 to 2023). "While BALF levels of dendritic cells, T or B cells were not significantly influenced by Rgs10 deficiency upon influenza infection, CCL20 could have specifically attracted or stimulated Th17 cells known to be activated during influenza infection and to recruit neutrophils to the airways." (PMID 34912341, 2021).
keloid (3 papers, 2018 to 2024). An irregularly shaped, elevated mark on the skin caused by deposits of excessive amounts of collagen during wound healing. "IL-17A, TNFAIP3, and CCL20 were found to be significantly increased in the keloid Th17 cells compared to the healthy skin Th17 cells." (PMID 39872534, 2024). "Our results associate keloid tissues with an inflammatory milieu representing multiple T-helper pathways, including the Th2 (e.g. IL-4R, CCL11, TSLP, TNFSF4/OX40L, TNFRSF4/OX40), Th1 (e.g. IFNγ, CXCL10/11), Th17/Th22 (e.g. PI3, CCL20, S100As) axes, as well as the JAK/STAT signaling molecule JAK3." (PMID 33329590, 2020).
kidney damage (3 papers, 2018 to 2024). "Combination of CCL20 with CCR6 (the CCL20 receptor) cause the recruitment of leukocyte subsets, which finally promote immune-mediated kidney damage." (PMID 30029622, 2018). "Both of these events, and potentially, further supported by additional CCL20 expression, would be expected to: (i) reduce allograft kidney damage, (ii) suppress T-cell recruitment to the kidney, and (iii) suppress activation of the innate and adaptive immune system." (PMID 34356678, 2021). "Plasma IL-8, IL-10, IL-17, C-C motif chemokine ligand 20 (CCL20), TNF-α and GDF15 correlated with kidney damage assessed as the magnitude of proteinuria." (PMID 39188767, 2024).
liver cirrhosis (3 papers, 2018 to 2023). "CCL20 and LCN2 were determined in all samples (HCC, 167; liver cirrhosis, 106; and healthy control, 106) and finally chosen for the construction of the combination model by binary logistic regression." (PMID 35308139, 2022). "The results suggested that several molecules were modulated, such as macrophage inflammatory protein 3α (MIP-3α)/chemokine ligand 20 (CCL20), nitric oxide (NO), thromboxane 2 (TXB2) and myeloperoxidase (MPO), indicating the therapeutic potential of probiotics on liver cirrhosis." (PMID 30297615, 2018). "We finally evaluated the performance of the CCL20/LCN2-based model (model_2) in discriminating HCC from the comprehensive control that includes all nontumor subjects and the control of patients with liver cirrhosis, which constitutes the highest risk group for the development of HCC." (PMID 35308139, 2022).
lupus (3 papers, 2019 to 2025). "Both RA and systemic lupus erythematosus (SLE) exhibit DCs accumulation at inflammatory sites, mediated by CCL20-dependent recruitment." (PMID 40924040, 2025).
lupus nephritis (3 papers, 2020 to 2024). Glomerulonephritis in the context of systemic lupus erythematosus. "The chemokine receptor CCR6, a nonpromiscuous receptor with as sole ligand C-C motif chemokine ligand 20 (CCL20), has been found to a play a key role in the trafficking of Th17 cells to the inflamed kidney in experimental lupus nephritis." (PMID 35620115, 2022). "Further investigation is needed to clarify the association of Fli-1 in CCL20 expression and infiltration of CCR6+ Th17 cells in lupus nephritis." (PMID 32183259, 2020).
lymph node metastasis (3 papers, 2019 to 2025). "Additional analyses using patient clinical information showed a strong correlation between elevated CCL20 expression and lymph node metastasis." (PMID 40444282, 2025). "The patients with axillary lymph node metastases with the concomitant CCL20 high expression and increased FOXP3+ TILs infiltration had the worst OS (P < .001)." (PMID 31852159, 2019). "The patients with axillary lymph node metastases with the concomitant CCL20 high expression and increased FOXP3+ TILs infiltration had the worst overall survival (OS) (P < .001), In lymph node-negative breast cancer patients, the status of CCL20 and FOXP3 was not related to OS (P = .22)." (PMID 31852159, 2019).
mastitis (3 papers, 2013 to 2022). Inflammation of breast tissue during lactation or postpartum due to an obstructed duct or infection. "Besides, CCL3, CCL4, CCL5 and CCL20 have also been reported as differentially expressed in response to mastitis by other investigators." (PMID 36336691, 2022). "We have shown that Ccl20 is expressed by bovine MEC in response to IL-17A and IL-17F, and Ccl20 has been shown by several groups to be a major response gene of bovine MEC exposed to MAMPs or mastitis-associated bacteria." (PMID 23696826, 2013).
mucositis (3 papers, 2019 to 2024). Mucositis is inflammation and damage of the mucous membranes lining the mouth and other parts of the gastrointestinal (GI) tract. "We investigated quantitative markers of mucositis including citrulline, CCL20 and REG3α in children with acute leukemia at the onset of fever." (PMID 37919603, 2024). "Mean concentration of CCL-20/MIP-3α in healthy sites was the lowest (33.24 ng/mL) when compared to peri-implant mucositis and peri-implantitis." (PMID 36077204, 2022). "In this feasibility study, CCL-20/MIP-3α, BAFF/BLyS, IL-23, RANKL, and Osteoprotegerin concentrations were assessed in patients diagnosed with peri-implant health, peri-implant mucositis and peri-implantitis." (PMID 36077204, 2022). "The outcomes showed that higher concentration of CCL-20/MIP-3α, BAFF, IL-23, and RANKL was present in sites with peri-implant mucositis/peri-implantitis compared to healthy peri-implant tissues." (PMID 36077204, 2022).
ovarian tumors (3 papers, 2016 to 2023). "The post-spreading of ovarian tumors shows high expression of CCL20/liver and activation-regulated chemokine (LARC), CXCL17, and CXCR4." (PMID 37108425, 2023). "The expression profiles in comparison with cell lines revealed that dominant chemokines expressed in ovarian tumor tissues are likely shifted from CXCL1-3 and 8 to CCL20." (PMID 27723802, 2016).
penile cancer (3 papers, 2020 to 2022). A primary or metastatic malignant neoplasm that affects the penis. "In a comparison of penile carcinoma patients with healthy controls, it was also shown that serological elevation of CCL20 has a worse prognosis." (PMID 36143149, 2022).
periodontal disease (3 papers, 2015 to 2021). "TLR3 stimulation in combination with IL-1β has previously been shown to initiate CCL20 upregulation in human gingival fibroblasts in periodontal disease, and our results indicate that this cellular mechanism can also be important in IBD." (PMID 26536229, 2015).
pneumococcal meningitis (3 papers, 2014 to 2025). An acute purulent infection of the meninges and subarachnoid space caused by Streptococcus pneumoniae, most prevalent in children and adults over the age of 60. "The neutrophil response in pneumococcal meningitis that is guided to the subarachnoid space through the chemokine/receptor pair CCL20/CCR6 is important for limiting bacterial outgrowth." (PMID 24699535, 2014). "CCR6-deficient mice with pneumococcal meningitis and WT mice with pneumococcal meningitis treated with anti-CCL20 antibodies both had reduced CSF white blood cell counts." (PMID 24699535, 2014). "To evaluate CCL20 during acute pneumococcal meningitis in humans we used patients from a nationwide prospective cohort study, performed from 2006–2010." (PMID 24699535, 2014). "Using protein array technology we showed that the chemokine CCL20 is up-regulated in the cerebrospinal fluid (CSF) of patients with pneumococcal meningitis." (PMID 24699535, 2014). "This missing difference in brain IL-22 levels argues against a critical role of this TH17-cytokine as a downstream mediator of CCL20/CCR6-induced leukocyte recruitment to the CSF in pneumococcal meningitis." (PMID 24699535, 2014). "Immunohistochemical staining was positive for CCL20 in the leukocyte infiltrate in the subarachnoid space and in the plexus epithelium in mice subjected to pneumococcal meningitis." (PMID 24699535, 2014). "In patients with pneumococcal meningitis, the median CSF CCL20 concentration was 6.9 ng/ml (interquartile range [IQR] 1.20–17.1)." (PMID 24699535, 2014). "Here, we assessed the role of CCL20 on cerebral inflammation by determining CCL20 levels in the CSF of patients with pneumococcal meningitis." (PMID 24699535, 2014). "In a prospective nationwide study, CCL20 levels were significantly elevated in the CSF of patients with pneumococcal meningitis and correlated with CSF leukocyte counts." (PMID 24699535, 2014). "Time course analysis in a well-established mouse model of pneumococcal meningitis demonstrated that CCL20 was exclusively up-regulated during the acute stage and levels returned to normal quickly after administration of antibiotic therapy." (PMID 24699535, 2014). "In conclusion, CCL20 was shown to be a crucial chemotactic chemokine during acute pneumococcal meningitis, attracting neutrophils to the subarachnoid space." (PMID 24699535, 2014). "Here, the semi-quantitative protein array data was confirmed by quantitative analysis using a Luminex assay, which showed markedly enhanced levels of CCL20 in the CSF of pneumococcal meningitis patients included in a large prospective cohort study." (PMID 24699535, 2014). "CCL20 can recruit Th17 cells, B cells, and dendritic cells, recruit granulocytes in pneumococcal meningitis, can have antimicrobial activity, and could induce MUC5AC mucin production in a human airway epithelial cell line." (PMID 40586572, 2025). "We previously identified CCL20 as an early chemokine in the cerebrospinal fluid (CSF) of patients with pneumococcal meningitis but its functional relevance was unknown." (PMID 24699535, 2014). "Thus, IL-17A/F seems unlikely to be involved in the chemoattractant activity of the CCL20/CCR6 axis during pneumococcal meningitis." (PMID 24699535, 2014). "Since [i] CCL20 attracts granulocytes in a Boyden chamber assay and [ii] intracisternal CCL20 injection leads to CSF pleocytosis with granulocytes as the predominant cell type, we postulate a direct chemotactic role of CCL20 in the recruitment of granulocytes in pneumococcal meningitis." (PMID 24699535, 2014). "Combined with the observation that blockage of CCL20 and deficiency of CCR6 reduced CSF pleocytosis after intracisternal pneumococcal challenge, our data indicate a crucial role of CCL20 in the recruitment of granulocytes to the subarachnoid space during pneumococcal meningitis." (PMID 24699535, 2014).
pneumococcal meningitis (continued). "High levels of CCL20 in the CSF of humans have been detected by protein array technology in patients with acute pneumococcal meningitis but not in control patients or in patients after recovery." (PMID 24699535, 2014). "Thus, it appears possible that expression of CCL20 is mediated by TLR2 and TLR4 activation during pneumococcal meningitis." (PMID 24699535, 2014). "Here we studied the role of CCL20 and its receptor CCR6 in pneumococcal meningitis." (PMID 24699535, 2014). "Thus, an antibacterial effect of CCL20 on S. pneumoniae does not seem to play a role in pneumococcal meningitis." (PMID 24699535, 2014). "Thus, IL-17 does not seem to mediate the pro-inflammatory effect of the CCL20/CCR6 axis in pneumococcal meningitis." (PMID 24699535, 2014).
post-traumatic stress disorder (3 papers, 2021 to 2023). An anxiety disorder precipitated by an experience of intense fear or horror while exposed to a traumatic (especially life-threatening) event. "In individuals with post-traumatic stress disorder (PTSD), there is an increase in serum levels of CCL13, CCL20, and CXCL6, which may indicate a higher risk for developing PTSD." (PMID 37153575, 2023).
primary biliary cholangitis (3 papers, 2023 to 2024). Primary biliary cholangitis (PBC) is a chronic and slowly progressive cholestatic liver disease of autoimmune etiology characterized by injury of the intrahepatic bile ducts that may eventually lead to liver failure. "The biliary epithelial cells release CC chemokine receptor 6 (CCR6) ligand 20 (CCL20), leading to recruitment of CCR6+ T cells and subsequent infiltration into the biliary epithelium in primary biliary cholangitis patients." (PMID 38405661, 2024).
Psoriasiform dermatitis (3 papers, 2023 to 2025). A skin abnormality characterized by redness and irritation, with thick, red skin that displays flaky, silver-white patches (scales). "Oral administration of deoxycholic acid significantly improved psoriasiform dermatitis in murine model, potentially by inhibiting IL-17A production and blocking CCL20-mediated trafficking." (PMID 39850616, 2025). "BAs can directly inhibit IL-17A production and block CCL20-mediated transport to ameliorate psoriasiform dermatitis with minimal toxicity." (PMID 38482003, 2024). "Inhibition of the CCL20/CCR6 axis attenuated experimentally induced psoriasiform dermatitis." (PMID 37049538, 2023).
pulmonary hypertension (3 papers, 2018 to 2024). Increased pressure within the pulmonary circulation due to lung or heart disorder. "Pulmonary arterial hypertension in individuals with SSc is associated with elevated serum CCL20 levels." (PMID 38653779, 2024). "Of these chemokines and chemokine receptors, Ccl2, Ccl7, Ccl20, Ccl21, Cxcl13, Cxcl4, Ccr6 and Ccr7 have already been demonstrated to be associated with pulmonary hypertension." (PMID 32176619, 2020).
rosacea (3 papers, 2021 to 2023). A chronic erythematous skin disorder that affects the face. "Directly activated expression of CCL20 through DEXA treatment in keratinocytes deteriorated skin conditions such as perioral dermatitis and rosacea." (PMID 34834106, 2021). "TNF-α and IL-1β are known to induce the expression of a subset of proinflammatory chemokines (CXCL1, CXCL8, CCL20, and CCL27) in keratinocytes, implying a potential pathway for TH1 and TH17 cell recruitment as well as neutrophil recruitment in rosacea lesional skin." (PMID 35832851, 2022).
Rotavirus infection (3 papers, 2015 to 2025). Infection with any of the rotaviruses. "CCL20 has direct antimicrobial and antiviral properties and the lack of its receptor causes a dampened humoral immune response to rotavirus infection." (PMID 39666439, 2025). "More recently, elevatedlevels of CCL20 have been reported in rotavirus infections." (PMID 41117538, 2025).
squamous cell carcinoma (3 papers, 2013 to 2023). A carcinoma arising from squamous epithelial cells. "It was also shown that the level of expression of CCL20 mRNA in the tumor tissue as well as miR-150 and linc00673 in the serum EVs can be used as a diagnostic marker differentiating adenocarcinoma from squamous cell carcinoma." (PMID 37316552, 2023). "A number of chemokine/chemokine receptor antagonists are being developed for tumour immunotherapy and it remains to be seen whether blocking of CCR6/CCL20 would impact on immunosuppression in squamous cell cancers." (PMID 23469070, 2013).
anaphylaxis (2 papers, 2022 to 2023). An acute hypersensitivity reaction that occurs from exposure to an allergen. "In addition, the selective elevation of IL-6 and a small panel of chemokines (CCL5, CCL20, CCL22, and CXCL1) in the spleen upon oral allergen but not saline challenge suggests their key role in eliciting anaphylaxis via the oral route." (PMID 36238931, 2022).
autoimmune neurological diseases (2 papers, 2019 to 2021). "CCL20 plays an important role in the pathogenesis of autoimmune neurological diseases." (PMID 31200452, 2019).
bacterial meningitis (2 papers, 2014 to 2024). Inflammation of the membranes surrounding the brain and spinal cord due to a bacterial infection. "Cytokines IL-2, IL-17A, and the chemokine MIP-3α (CCL20) have also been shown to be associated with bacterial meningitis and promote BBB disruption (46, –, 49)." (PMID 39400158, 2024). "CCL20 levels in negative controls and patients with viral meningitis were significantly lower than those of bacterial meningitis patients." (PMID 24699535, 2014).
celiac disease (2 papers, 2026). An autoimmune genetic disorder with an unknown pattern of inheritance that primarily affects the digestive tract. "Upon barrier compromise as seen in celiac disease and IBD, CCL20 and IL-18 might be able to drive immune cell migration to the lamina propria which might explain the reported beneficial effect of an gluten-free diet and increased serum CCL20 and IL-18 levels in celiac patients." (PMID 41585485, 2026).
cerebral infarction (2 papers, 2020 to 2024). An ischemic condition of the brain, producing a persistent focal neurological deficit in the area of distribution of the cerebral arteries. "The expression of CCL20 and CCR6 was found to be upregulated in ischemic brain injury, while a CCL20-neutralizing antibody reduced the volume of cerebral infarction in mice." (PMID 38612597, 2024). "The expression of CCL20 and its cognate receptor CC chemokine receptor 6 (CCR6) was upregulated in ischemic brain injury, while CCL20-neutralizing antibody reduced the volume of cerebral infarction." (PMID 32575072, 2020).